ACKR2 (atypical chemokine receptor 2)
Diseases named in the same sentence as ACKR2 in open-access papers (continued):
Sharing a sentence is not in itself a finding about the gene and the disease.
Lymphadenopathy (1 paper, 2024). Enlargement (swelling) of a lymph node. "Thus, the extent of splenomegaly and lymphadenopathy was comparable between female WT- and Ackr2-/- B6lpr mice, as were numbers of CD3+CD4-CD8- autoreactive T cells in spleen, lymph nodes and kidneys, levels of circulating lupus autoantibodies and the extent of glomerular IgG deposition." (PMID 38799420, 2024).
lymphoproliferative syndrome (1 paper, 2024). A disorder characterized by proliferation of lymphocytes at various stages of differentiation. "Female WT- and Ackr2-/- B6lpr mice developed a lymphoproliferative syndrome evident from spleen and total lymph node weights." (PMID 38799420, 2024).
multiple sclerosis (1 paper, 2017). A progressive autoimmune disorder affecting the central nervous system resulting in demyelination. "Concordant to evidence in multiple sclerosis experimental models, our data corroborate a distinct role for ACKR2 in cerebral inflammatory processes compared to its reported functions in peripheral tissues." (PMID 29176798, 2017).
Obesity (1 paper, 2022). Accumulation of substantial excess body fat. "Improved hypothalamic inflammation and reduced obesity-related glucose intolerance were achieved by hypothalamic lentiviral overexpression of ACKR2." (PMID 35677043, 2022). "It is therefore hypothesized that increased expression of ACKR2 in the hypothalamus lowers diet-induced inflammation, which in turn improves glucose tolerance in obesity-prone mice." (PMID 35677043, 2022). "Thus, ACKR2 appears as a novel immunomodulatory actor in the setting of diet-induced inflammation of the hypothalamus, and approaches aimed at raising ACKR2 hypothalamic expression may be practical for enhancing metabolic control in obesity." (PMID 35677043, 2022).
peritonitis (1 paper, 2019). Inflammation of the peritoneum (tissue that lines the abdominal wall and covers most of the organs in the abdomen). "For example, ACKR2 deficiency in a murine zymosan A-initiated peritonitis mouse model was shown to promote macrophage efferocytosis, suggesting an important potential function of ACKR2 in atherosclerotic plaques with regards to the efficiency of foam cell efferocytosis." (PMID 31191301, 2019).
polyp (1 paper, 2020). A usually exophytic mass attached to the underlying tissue by a broad base or a thin stalk. "On average, ACKR2 was downregulated in neoplastic as compared to non-affected tissue in polyp (by 2.7-fold) and cancer (by 3.1-fold) patients." (PMID 33374792, 2020).
pulmonary fibrosis (1 paper, 2024). Chronic progressive interstitial lung disorder characterized by the replacement of the lung tissue by connective tissue, leading to progressive dyspnea, respiratory failure, or right heart failure. "Elevated Ccl5 levels are associated with the influx of Ccr5+ IFNγ-producing γδ T cells, mitigating lethality and lung fibrosis in Ackr2-/- mice, revealing a potential role of CCL5 counterbalancing pulmonary fibrosis triggered by bleomycin." (PMID 39768150, 2024). "In contrast, Ackr2-/- mice show reduced lethality, lung fibrosis, tissue-remodeling gene expression, leukocyte influx, pulmonary injury, and dysfunction induced by bleomycin." (PMID 39768150, 2024). "In mice lungs, Ccl5 is produced after bleomycin instillation, associated with the influx of Ccr5+ IFNγ-producing γδ T cells, attenuating lung fibrosis in Ackr2-/- mice." (PMID 39768150, 2024). "Ackr2 is expressed by blood endothelial cells and experiments with bone marrow chimeras highlight the pivotal role of endothelial cell Ackr2 expression in bleomycin-induced pulmonary fibrosis." (PMID 39768150, 2024). "Increased levels of Ccl12 may drive the Ccr2+ IFNγ-producing γδ T cell, reducing pulmonary fibrosis triggered by bleomycin in Ackr2-/- mice." (PMID 39768150, 2024).
rheumatic diseases (1 paper, 2021). "Leucocyte infiltration, inflammatory mediators and atypical chemokine receptor 2 (ACKR2) expression in SSc placentas were compared with those in other rheumatic diseases (ORD) and healthy controls (HC)." (PMID 33313931, 2021).
Sepsis (1 paper, 2022). Sepsis is defined as life-threatening organ dysfunction caused by a dysregulated host response to infection. "Using a cecal ligation and puncture (CLP, the most frequently used model for inducing sepsis) murine model, it was demonstrated that ACKR2-deficient mice had a significantly lower survival rate compared with similarly treated WT mice." (PMID 35677043, 2022). "When compared to WT mice, ACKR2–/– mice had more neutrophil infiltration and higher levels of inflammatory CC chemokine in the lung, heart, and kidney, indicating that ACKR2 regulates neutrophil infiltration and chemokine accumulation in secondary organs during sepsis." (PMID 35677043, 2022).
serous carcinoma (1 paper, 2022). "Metastasis of high-grade serous carcinoma may be related to the interaction between high expression of ACKR2 chemokine receptor and cytokines such as CCL5." (PMID 35935940, 2022).
silicosis (1 paper, 2024). Silicosis is a respiratory disease caused by breathing in (inhaling) silica dust. "Upregulation of cytokines including TNFs,IFN-β precursor, IL-6, atypical chemokine receptor 2, TNFR13BV, and mutantIL-17F may be implicated in the exacerbated, persistent immune response and fibrosisthat occur during the development of silicosis." (PMID 39606764, 2024).
Stillbirth (1 paper, 2020). Death of the fetus in utero after at least 22 weeks of gestation. "It has been shown that Ackr2 deficiency in mice leads to abnormal placenta structure, increases the incidence of stillbirth, and reduces neonatal survival." (PMID 33250783, 2020).
thyroid (1 paper, 2017). "In thyroid neoplastic cells miR-146a up-regulation blocks D6/ACKR2 expression allowing chemokines to induce leukocytes migration in tumor microenvironment thereby promoting cancer progression." (PMID 28740576, 2017).
tumor (43 papers, 2013 to 2025). "ACKR2 loss is linked to enhanced initial tumor development and protection against metastasis in a NeuT-driven primary mammary carcinogenesis." (PMID 35677043, 2022). "ACKR2-deficient mice were shown to be more prone to tumour development but display increased tumour natural killer (NK) cell infiltration and circulating neutrophils, while opposing effects were reported regarding ACKR2 involvement in tumour dissemination." (PMID 33801414, 2021). "In a model of NeuT-driven primary mammary carcinogenesis ACKR2 deficiency is associated with increased primary tumor growth and protection against metastasis." (PMID 29445158, 2018). "Unexpectedly, in the same model, we found that ACKR2 deficiency was associated with protection against metastasis, an observation in sharp contrast with the primary tumor phenotype." (PMID 29445158, 2018). "We next evaluated whether the tumor growth inhibition observed in Ackr2-targeted B16-F10 cells is associated with changes in immune cell infiltration, likely driven by altered availability of key chemokines such as CCL5 and CXCL10." (PMID 40248897, 2025). "Moreover, downregulation of ACKR2 in transformed cells has been associated with tumor progression and oncogene activation in Kaposi sarcoma." (PMID 29445158, 2018). "Tuning of monocyte recruitment underlies the regulatory function of ACKR2 in tumor progression." (PMID 29445158, 2018). "However, another study found that genetic deficiency of the atypical chemokine receptor 2 (Ackr2-/-) in Apcmin/+ mice led to reduced tumour burden, which the authors attributed to an increase in mast cells that can recruit CD8+ T cells through leukotriene B4 (LTB4)." (PMID 36263033, 2022). "Mechanistically, concurrent chemoradiotherapy triggers expression of atypical chemokine receptor 2 (ACKR2) on tumor cells, thus increasing the production of TGF-β and driving T cell senescence." (PMID 40860134, 2025). "Expanding research to investigate the impact of ACKR2 targeting in additional tumor models would provide broader insights into its therapeutic applicability." (PMID 40248897, 2025). "We next assessed tumor growth in both control and Ackr2-targeted B16-F10 cells, generated using shRNA, in immunodeficient NOD SCID gamma (NSG) mice, which lack T, B, and NK cells, and in immunocompetent C57BL/6 mice." (PMID 40248897, 2025). "Targeting Ackr2 led to tumor growth inhibition, improved survival, and enhanced response to anti-PD-1 therapy." (PMID 40248897, 2025). "We first investigated the effects of genetically targeting Ackr2 on the release by tumor cells of two chemokines, CCL5 and CXCL10, which can be scavenged by ACKR27 and have high affinity for this receptor." (PMID 40248897, 2025). "The most interesting observation emerging from our data is that CXCL14 promotes tumor metastasis through ACKR2 in NSCLC cells." (PMID 37056937, 2023). "Of note, CXCL10 is a pivotal inflammatory CXC chemokine in many physiological and pathological processes, including angiogenesis, chronic inflammation, immune dysfunction, tumor development and dissemination, in which ACKR2 was also shown to be involved." (PMID 37153591, 2023). "Results have demonstrated that the expression ratio of ACKR2 was decreased through normal to tumor and increasing depth of tumor invasion." (PMID 35677043, 2022). "As a result, ACKR2 expression in the tumor microenvironment decoys CCL2 and impairs the infiltration of NK cells." (PMID 35677043, 2022). "CCL22, a Treg-recruiting chemokine, was another chemokine that was increased in the ACKR2-decreased tumor tissues, showing that ACKR2 downregulation also promotes tumor development by creating an immunosuppressive tumor microenvironment." (PMID 35677043, 2022). "ACKR2 was also highly expressed in endothelial cells of the blood and lymphatic vessels of unaffected tissues compared with tumor tissues." (PMID 35677043, 2022).
tumor (continued). "Given the frequent concurrent up-regulation of CXCR4/ACKR2 and ErbB family receptors in BC and their shared relevance for tumor growth and metastasis occurrence, investigating their interplay mechanisms in tumor contexts is of utmost importance." (PMID 36233192, 2022). "The roles of ACKR1 and ACKR2 in tumor growth have also been evaluated in other cancer types where their expression has been correlated with a reduced tumor growth and survival benefit." (PMID 35008294, 2021). "Our study sheds new light on the complexity of the chemokine network and the potential role of CXCL10 regulation by ACKR2 in tumour immunology." (PMID 33801414, 2021). "Overall, our study sheds new light on the complexity of the chemokine network and the potential role of CXCL10 regulation by ACKR2 in many physiological and pathological processes, including tumour immunology." (PMID 33801414, 2021). "In many cases, ACKR2 inhibited the infiltration of tumor-supporting leukocytes, angiogenesis or tumor cell invasion; often, these processes were accompanied by reduced levels of the relevant chemokines and competition with CCR2-mediated signaling." (PMID 32582148, 2020). "By virtue of its expression by lymphatic endothelial cells and by tumor cells, ACKR2 plays key roles in preventing inflammatory conditions in a variety of settings, and was mainly referred to as tumor-restricting receptor." (PMID 32582148, 2020). "In contrast, ACKR1, ACKR4 and in many cases also ACKR2 exert anti-tumor functions at conventional migration-related processes as well as at non-conventional aspects." (PMID 32582148, 2020). "The expression ratio (normal-to-tumor) of ACKR2 insignificantly decreased along with increasing tumor grade (G1-G2-G3) (ρ = −0.27, p = 0.069), owing to insignificant increase of ACKR2 expression in tumors (ρ = 0.27, p = 0.065)." (PMID 33374792, 2020). "By functioning in these manners, the tumor-restricting but also the tumor-promoting activities of ACKR2 resulted from the expected, motility-related functions that are involved in cancer progression." (PMID 32582148, 2020). "The expression ratio (normal-to-tumor) of ACKR2 decreased along with an increasing depth of tumor invasion (T0/1-T2-T3-T4), while that of ACKR4 did not display significant association (ρ = −0.15, p = 0.283)." (PMID 33374792, 2020). "In the context of solid tumors, ACKR2 acts as one mechanism of cancer immunoediting by preventing tumor growth, regulating pro-tumoral leukocyte infiltration." (PMID 32957704, 2020). "Of the individual TNM staging system components, ACKR2 expression was negatively correlated with the depth of tumor invasion (T)." (PMID 33374792, 2020). "On the contrary, ACKR2 has a tumor promoting role in the Apc-Min model of CRC limiting mast cells infiltration and activation of CD8+ T cells and it has a pro-metastatic function in breast and melanoma cancer models, by limiting neutrophil and NK activity." (PMID 30894861, 2019). "We therefore focused on effects of ACKR2 genetic inactivation on the myeloid compartment of tumor-bearing mice as a potential mechanism of protection from metastasis." (PMID 29445158, 2018). "Accordingly, genetic inactivation of ACKR2 unleashes tumor-promoting inflammation in the skin and gastrointestinal (GI) tract." (PMID 29445158, 2018). "To examine roles for Ackr2 in metastasis from a primary tumor, we crossed Ackr2−/− mice onto the PyMT background." (PMID 30158126, 2018). "ACKR2 was found to be protective in cancer progression also when expressed by tumor cells, by inhibiting inflammatory chemokines and protumoral leukocyte infiltration." (PMID 28123388, 2016). "In these contexts, ACKR2 functions essentially as a tumor suppressor gene by limiting tumor-promoting tissue inflammatory responses." (PMID 27375622, 2016).
tumor (continued). "We believe that achieving therapeutic efficacy with ACKR2 inhibition, while minimizing side effects, requires integrative approaches and a comprehensive understanding of the unique immune context and chemokine profile of each tumor." (PMID 40248897, 2025). "For instance, in inflammation-driven tumor models, the absence of ACKR2 leads to increased tumor growth linked to unchecked inflammation." (PMID 41516196, 2025). "However, both genetic targeting and pharmacological inhibition of ACKR2 with an anti-ACKR2 antibody significantly reduced B16-F10 tumor growth." (PMID 40248897, 2025). "Notably, Ackr2−/− mice showed enhanced tumor growth, but they were more protected against tumor metastasis through a neutrophil-dependent mechanism." (PMID 37444436, 2023). "In addition to the tumor-inhibitory effects of ACKR2, it has also been shown that this decoy chemokine receptor has been involved in tumor progression." (PMID 35677043, 2022). "In cancer, ACKR2 exerts conflicting roles, either tumor-promoting or tumor-suppressing." (PMID 35677043, 2022). "Moreover, ACKR2 expression in tumor tissues was negatively correlated to tumor invasiveness, as its expression was lower in T3 and T4 grades than in T1 and T2 ones." (PMID 35677043, 2022). "For ACKR3, ERK and AKT activation has been shown to be essential in promoting cancer cell survival, proliferation and tumor angiogenesis, whilst the biological relevance for ACKR2 is still unknown." (PMID 36483536, 2022). "On the one hand, ACKR2 inhibits the recruitment of tumor-promoting cells and suppresses tumor-promoting inflammation to blockade inflammatory responses that are favorable for tumor growth." (PMID 35677043, 2022). "The atypical chemokine receptor ACKR2 plays an important role in the tumour microenvironment." (PMID 33801414, 2021). "CXCL10 is one of the most important inflammatory CXC chemokines and is involved in many physiological and pathological processes such as angiogenesis, chronic inflammation, immune dysfunction, tumour development and dissemination, in which ACKR2 has also been shown to play critical roles." (PMID 33801414, 2021). "Because of its increased relevance in inflammation and tumor biology, insights into ACKR2 signaling properties may lead to the identification of new therapeutic approaches acting on the regulation of innate and adaptive immune responses." (PMID 32957704, 2020). "However, in addition, ACKR2 was found to restrict tumor progression by regulating atypical chemokine activities at the tumor setting, such as cancer cell proliferation." (PMID 32582148, 2020). "CXCL14 also stimulated ACKR2 to mediate tumor invasion and metastasis." (PMID 32708730, 2020). "Additionally, increased ACKR2 expression correlated inversely with tumor severity to lymph node metastasis as well as with clinical stages, but positively correlated to disease-free survival rate in cancer patients." (PMID 32456359, 2020). "Taken together, these results indicate that the chemokine scavenger activity of ACKR2 may act mainly as protective factor from cancer growth, when recruited leukocytes sustain and enhance the tumor growth." (PMID 32456359, 2020). "Functionally, ACKR2 played a significant role in gut inflammation and cancer as knock-out mice had more severe inflammation and were prone to inflammation-induced cancer, gaining the ACKR2 gene a tumor suppressor label." (PMID 33374792, 2020). "However, through the same mechanisms of CCL2/CCR2 inhibition, ACKR2 was also reported to prevent the activities of beneficial leukocyte sub-populations, such as NK cells and neutrophils that are cytotoxic against tumor cells." (PMID 32582148, 2020). "Moreover, the downregulation significantly decreased along with the disease advancement, although even at stage IV CRC, ACKR2 remained downregulated in the tumor as compared to matched normal mucosa (by 1.3-fold)." (PMID 33374792, 2020).